TNK2 (tyrosine kinase non receptor 2)
Diseases named in the same sentence as TNK2 in open-access papers (continued):
Sharing a sentence is not in itself a finding about the gene and the disease.
Hypertension (1 paper, 2023). The presence of chronic increased pressure in the systemic arterial system. "TNK2 gene was involved in the oxidative damage response pathway, and it was demonstrated that inflammation and oxidative stress significantly contributed to the vascular dysfunction and renal damage associated with hypertension." (PMID 36869404, 2023). "TNK2 was involved in the oxidative damage response pathway that could cause vascular dysfunction and renal damage associated with hypertension." (PMID 36869404, 2023).
infantile epilepsy (1 paper, 2024). "We considered TNK2, encoding a nonreceptor tyrosine kinase previously linked to infantile epilepsy, as a potential disease-causing candidate." (PMID 39246740, 2024).
infantile-onset epilepsy (1 paper, 2024). Epilepsy starting in the first 12 months of life, including self-limiting and refractory seizures, and epilepsies with and without developmental disorders. "The TNK2 gene-related neurodevelopmental disorder is characterized by infantile-onset epilepsy, intellectual disability, speech, and cognitive delay." (PMID 39493104, 2024).
lymphoma (1 paper, 2019). A malignant (clonal) proliferation of B- lymphocytes or T- lymphocytes which involves the lymph nodes, bone marrow and/or extranodal sites. "To corroborate these findings, we analyzed EMCV and CVB3 infection in commercial Hap1 cells (a haploid hematopoietic-derived lymphoma cell line) deficient in TNK2." (PMID 31769754, 2019).
Parkinson disease (1 paper, 2023). A progressive degenerative disorder of the central nervous system characterized by loss of dopamine producing neurons in the substantia nigra and the presence of Lewy bodies in the substantia nigra and locus coeruleus. "Importantly, variants in the human TNK2 gene are associated with Parkinson's disease, and TNK2/SID-3 is involved in the endocytic regulation of dopamine and effectors of epigenetic gene silencing." (PMID 37309665, 2023).
poliovirus infection (1 paper, 2019). An disease or disorder caused by infection with Enterovirus C. "Statistically significant reductions in poliovirus infection in both Hap1 and A549 TNK2 knockout cells and reduction in enterovirus D68 infection in A549 cells were also observed (E F)." (PMID 31769754, 2019).
cancer (59 papers, 2008 to 2025). A tumor composed of atypical neoplastic, often pleomorphic cells that invade other tissues. "Several investigations have connected various types of cancers to the abnormal activation of tyrosine kinases (TNK2) caused by somatic mutation or DNA amplification." (PMID 38136890, 2023). "The TNK2 gene on chromosome 3q29 codes for the ACK1 protein, which is linked to various human cancer." (PMID 36830587, 2023). "Orthologs of sid-3 are present in a wide range of organisms; the human ortholog ACK1/TNK2 has a wide range of reported substrates for its kinase activity and has been implicated in various cancers." (PMID 28874467, 2017). "Disruption of TNK2 leads to reduced cell growth, halted cell cycle progression, increased apoptosis, and heightened susceptibility to radiation, suggesting that TNK2 has promise as a potential target for treating malignant tumors." (PMID 38650011, 2024). "ACK1 is an epigenetic regulator, and its coding gene TNK2 is related to hematological malignancies and other types of cancers." (PMID 35494626, 2022). "ACK1/TNK2 mRNA expression levels were significantly elevated in many types of cancers, including LUAD and LUSC." (PMID 32793482, 2020). "Overexpression of TNK2 in cancer cell lines can increase the invasive phenotype, both in vitro and in vivo, resulting in increased mortality of a mouse model of metastasis." (PMID 27902967, 2017). "Pathway analysis conferred that TNK2 has been correlated with several different growth signaling pathways and is known to regulate some of the most important growth regulators in cancer cells." (PMID 20718987, 2010). "Considering the relation between stem cells self-renewal maintenance and cancer cells development, Tnk2 also appears to be a promising candidate for qualifying as a bona-fide MSMG." (PMID 21176149, 2010). "In accordance, TNK2 overexpression was shown to promote invasion of cancer cells – but the mechanism by which TNK2 mediates these effects is unresolved." (PMID 18435854, 2008). "Surbhi Chouhan and colleagues' research revealed TNK2-mediated mitochondrial energy regulation as a vulnerability of PCa cells, and provided evidence for TNK2 inhibitors as potential therapeutic strategies inducing cancer-specific mitochondrial autophagy." (PMID 38774081, 2024). "We then used CCLE and EMBL-EBI to analyze TNK2 expression in cancer cell lines." (PMID 34421982, 2021). "Nonetheless, it is interesting to note that all the functions attributed to TNK2 so far point to the fact that this gene might play a significant role in the development and progression of cancer." (PMID 20718987, 2010). "To investigate the functional consequences of the observed TNK2/EGFR interaction, we wanted to examine how EGFR dynamics might be affected in cancer cells in which TNK2 had been silenced by siRNA treatment." (PMID 18435854, 2008). "Furthermore, our findings suggest that TNK2 is potentially an attractive target for EGFR-dependent cancers or for cancers where the only available drugable receptor is the EGFR." (PMID 18435854, 2008). "Thus, TNK2 has been treated as a beneficial tumor promoter in many cancer types." (PMID 34421982, 2021). "Also, TNK2 performed a momentous function in different cancers." (PMID 34421982, 2021). "Expression validation in the transcriptome, TCGA–BLCA, and GSE13507 datasets confirmed the up-regulation of APOL1, DHX34, and TNK2, and the down-regulation of AHNAK, CSPG4, NCAM1, and PCDHB4 in the cancer group." (PMID 40908816, 2025). "Another study suggested that TNK2 is an independent prognostic marker of HCC, which promotes cancer progression by downregulating WWOX and activating AKT signaling." (PMID 34421982, 2021). "Cross-cancer alteration analysis for Abl-1, EGFR, Fyn, LCK, Src, ACK1 (TNK2) tyrosine kinases reveal that these genes are frequently altered in cancers, e.g. EGFR and TNK2 are recurrently amplified and mutually exclusive in a majority of the cancer cases." (PMID 26546517, 2015).
cancer (continued). "We used siRNA to knockdown expression of TNK2 and its proposed effector BCAR1 in order to analyse the effect of this knockdown on cancer cell behaviour in vitro." (PMID 18435854, 2008). "Activated Cdc42‐associated kinase 1 (ACK1; gene name TNK2) is an ubiquitously expressed nonreceptor tyrosine kinase (non‐RTK) that is frequently amplified and mutated in different human cancers." (PMID 33730447, 2021). "Importantly, no functional effects of the TNK2/EGFR interaction have been established in a cancer context to date – and, more importantly, it is not known how aberrant expression of EGFRs often found in cancer cells affects this protein–protein interaction." (PMID 18435854, 2008). "In the present study we sought to investigate whether negative targeting of TNK2 by siRNA could be used to inhibit cancer cell invasion, to establish the contribution of its effect on the EGFR and to consequently attempt to resolve the issue of TNK2's mechanism of action." (PMID 18435854, 2008). "ACK1/TNK2 is a nonreceptor tyrosine kinase (NRTK) that represents a paradigm of tyrosine kinase signalling and seems to be addictive to cancer cells." (PMID 35057760, 2022).
tumor (48 papers, 2008 to 2025). "The deregulated TNK2 acts as a carcinogenic factor and is associated with tumor progression and patients’ overall survival." (PMID 38650011, 2024). "Ack1 (activated cdc42-associated kinase, also known as Tnk2) is a nonreceptor tyrosine kinase that is overexpressed in several different tumor types, including prostate, and enhances tumor growth and invasion and metastasis." (PMID 25950519, 2015). "The functional analysis of Ack1/Tnk2 helped address the mechanisms whereby these kinases regulate tumor growth and resistance to anticancer agents." (PMID 39123481, 2024). "The qRT-PCR findings indicated that the mRNA levels of ZNF692 and TNK2 were reduced in the tumor formed by cells with suppressed ZNF692 compared to the tumors induced by control cells." (PMID 38650011, 2024). "TNK2 caught our interest due to its involvement in tumor growth and its ability to activate MAPK/ERK signaling." (PMID 38650011, 2024). "To test the role of TNK2 in tumor growth in vivo, we established orthotopic xenograft using Tet-ON shTNK2 or shCTRL HCC1395 cells transplanted into mammary fat pads of NOD-SCID mice." (PMID 27902967, 2017). "Mice deficient in the Tnk2 gene encoding Ack1, are characterized by diminished CSK Y18-phosphorylation and spontaneous activation of CD8+ and CD4+ T cells, resulting in inhibited growth of transplanted ICB-resistant tumours." (PMID 36376335, 2022). "Detection of AKT Tyr176-phosphorylation in TNBCs, its sensitivity to TNK2 inhibitor (R)-9bMS which in turn compromising proliferation of TNBCs indicate that TNK2-AKT signaling may drive TNBC tumor growth." (PMID 27902967, 2017). "This hypothesis was supported by the finding that amplification of the TNK2 gene and mRNA, in primary tumours, correlates with poor prognosis." (PMID 18435854, 2008). "Amplification of the TNK2 gene in primary tumours correlates with poor prognosis." (PMID 18435854, 2008). "As previously discussed, the constitutive activation of signaling pathways like JAK-STAT and SRC/TNK2 in CSF3R-altered neoplasms presents opportunities for targeted interventions with documented efficacy using JAK inhibitors such as ruxolitinib in these neoplasms." (PMID 40806796, 2025). "Conversely, AR can bind to the NXTAR promoter and inhibit AR expression using a small molecule inhibitor of ACK1/TNK2, thereby inhibiting the proliferation of enzalutamide-resistant cells and reducing enzalutamide resistance during tumor therapy." (PMID 39655078, 2024). "By performing genetic ablation studies, we have demonstrated that TNK2 expression not only drives TNBC proliferation but also confers invasiveness, which is reflected in tumor formation in xenograft mouse models." (PMID 27902967, 2017). "We demonstrate that knockdown of TNK2 expression can substantially suppress the invasiveness and proliferation advantage of TNBC cells in vitro and tumor formation in xenograft mouse models." (PMID 27902967, 2017). "Although our study and previous studies have revealed the significant role of MOF in tumor progression through modulating the expression of various genes, such as SIRT6 and TNK2, more studies are needed to comprehensively understand the function and complex regulatory mechanism of MOF in the future." (PMID 35252011, 2022). "Owing to the wide range of different tumour subcategories and levels of EGFR expression within basal-like tumours, it is significant that we can demonstrate here the effectiveness of silencing TNK2 even when the EGFR pathway is active but not hyperactivated." (PMID 18435854, 2008). "Conversely, proteins hypophosphorylated (Tumor/Normal phosphorylation spectral count ratio >1) in tumors include the transcription factors STAT1 and STAT5, the protein tyrosine phosphatase PTPN11, the G-protein coupled receptor GPRC5A, and the kinases MAPK1, MAPK3, and TNK2." (PMID 19946374, 2009).
infection (3 papers, 2019 to 2025). The state of being infected such as from the introduction of a foreign agent such as serum, vaccine, antigenic substance or organism. "Specifically, genetic screens conducted to uncover effectors of Orsay virus infection identified the nck-1 and wsp-1 genes, which encode the worm orthologs of known interactors of mammalian TNK2/ACK1 necessary for infection by multiple forms of picornaviruses." (PMID 35984862, 2022). "We next attempted to rescue the EMCV infection defect in TNK2 knockout cells by ectopic overexpression of TNK2." (PMID 31769754, 2019). "In a multi-step growth curve, EMCV titers in the supernatant from TNK2 KO1 were 1660-fold lower at 24 hr post infection (p<0.01) and CVB3 titers in the supernatant from the TNK2 KO1 were 154-fold lower at 36 hr post infection (p<0.01)." (PMID 31769754, 2019). "A multi-step growth analysis showed that wild type primary lung fibroblast had more than 10-fold higher virus production than Tnk2 knock out cells at 6 hr post infection (p<0.01)." (PMID 31769754, 2019). "Together, these data demonstrated an important role for TNK2 in EMCV infection in an in vivo mouse infection model." (PMID 31769754, 2019). "Lentivirus expression of each of the three major TNK2 isoforms (which yielded expression levels of TNK2 much higher than the endogenous levels) in control A549 cells led to statistically significant reductions in EMCV infection (B C)." (PMID 31769754, 2019). "Here we demonstrate roles for three human genes, TNK2, WASL, and NCK1, in infection by multiple picornaviruses." (PMID 31769754, 2019). "After screening a panel of mammalian viruses, we found that multiple picornaviruses, including EMCV, CVB3, enterovirus D68, and poliovirus, rely on TNK2, WASL, and NCK1 for infection in different cell lines." (PMID 31769754, 2019). "In the current study, infection of mice lacking TNK2 by oral gavage, the analogous route of infection as for Orsay virus infection of C elegans, led to increased survival of animals deficient in TNK2." (PMID 31769754, 2019). "In the absence of either TNK2 or WASL, EMCV particles continued to accumulate in early endosomes at 30 min post infection in contrast to control cells, demonstrating a role for both genes in endosomal trafficking." (PMID 31769754, 2019).
TNK2 also shares sentences with these, for which no sentence is quoted: hepatocellular carcinoma (10 papers); melanoma (7); prostate tumor (6); lung adenocarcinoma (5); renal carcinoma (5); Autoimmunity (4); breast tumor (4); autoimmune disease (3); Lupus (3); acute myeloid leukemia (2); chronic myelomonocytic leukemia (2); chronic neutrophilic leukemia (2); esophageal cancer (2); glioblastoma (2); head and neck squamous cell carcinoma (2); acute lymphoblastic leukemia (1); basal cell carcinoma (1); benign prostatic hyperplasia (1); benign skin tumors (1); cervical cancer (1); chronic hepatitis C (1); colitis (1); colorectal tumors (1); diffuse gastric adenocarcinoma (1); embryonal carcinoma (1); gastric adenocarcinoma (1); gastric intestinal adenocarcinoma (1); gastric tumor (1); head and neck cancer (1); hematological malignancies (1).
A further 17 diseases each share a sentence with TNK2 in 1 paper.